DHRS7C (dehydrogenase/reductase 7C)
Description:
NADH-dependent oxidoreductase which catalyzes the oxidation of all-trans-retinol to all-trans-retinal. Plays a role in the regulation of cardiac and skeletal muscle metabolic functions. Maintains Ca(2+) intracellular homeostasis by repressing Ca(2+) release from the sarcoplasmic reticulum (SR) in myotubes, possibly through local alternations in NAD/NADH or retinol/retinal. Also plays a role in Ca(2+) homeostasis by controlling Ca(2+) overload in the cytosol and the SR in myotubes. Involved in glucose uptake into skeletal muscles and muscle performance by activating PI3K and mTORC2-mediated AKT1 phosphorylation signaling pathways, possibly through the action of its downstream catalytic product all-trans-retinoic acid.
Synonyms: SDR32C2
Tractability: Antibody: UniProt predicts a signal peptide or a membrane-spanning region.
Gene: Protein-coding gene on chromosome 17 (9,771,434 to 9,791,592, reverse strand). Ensembl gene ENSG00000184544.
Subcellular location: Sarcoplasmic reticulum membrane
Gene Ontology:
Molecular function: all-trans-retinol dehydrogenase (NAD+) activity; oxidoreductase activity, acting on the CH-OH group of donors, NAD or NADP as acceptor
Biological process: D-glucose import across plasma membrane; intracellular calcium ion homeostasis; regulation of release of sequestered calcium ion into cytosol by sarcoplasmic reticulum
Cellular component: longitudinal sarcoplasmic reticulum; sarcoplasmic reticulum membrane; bounding membrane of organelle; cytoplasm
Genetic constraint (gnomAD): Loss-of-function variants: 28 observed, 29.6 expected, observed/expected ratio (o/e) 0.95, 90% interval 0.7 to 1.3. The upper end of that interval is the gene's LOEUF score, 1.3, which puts it in group 5 of 6, group 1 being the genes least tolerant of losing a copy. Missense variants: 403 observed, 396.5 expected, observed/expected ratio (o/e) 1.02, 90% interval 0.94 to 1.1. Synonymous variants: 158 observed, 160.83 expected, observed/expected ratio (o/e) 0.98, 90% interval 0.86 to 1.12.
Homologues: Orthologues: chimpanzee DHRS7C (100% identical), macaque DHRS7C (98% identical), dog DHRS7C (95% identical), pig DHRS7C (93% identical), rabbit DHRS7C (93% identical), mouse Dhrs7c (91% identical), rat Dhrs7c (90% identical), guinea pig DHRS7C (88% identical), tropical clawed frog dhrs7c (66% identical), zebrafish dhrs7cb (57% identical), zebrafish dhrs7ca (48% identical), Drosophila melanogaster CG7601 (32% identical), and 11 more. Paralogues in human: DHRS7B (42% identical), DHRS7 (23% identical), RDH8 (22% identical), DHRS2 (20% identical), HSD11B1 (20% identical), HSD11B1L (19% identical), DHRS4 (18% identical), CBR1 (16% identical), DHRS11 (16% identical), CBR3 (16% identical), HSDL2 (16% identical), DHRS4L2 (15% identical), and 1 more.
Diseases named in the same sentence as DHRS7C in open-access papers:
DHRS7C is named in the same sentence as 5 diseases in open-access papers, as found by Europe PMC text mining. Sharing a sentence is not in itself a finding about the gene and the disease. The quoted sentences say what the papers report.
colorectal cancer (1 paper, 2024). A primary or metastatic malignant neoplasm that affects the colon or rectum. "A model for the early-stage screening of colorectal cancer was created using seven consensus biomarkers (namely ESM1, DHRS7C, OTOP3, AADACL2, LPHN3, GABRD, and LPAR1), and yielded >98% balanced accuracy on external validation." (PMID 39484215, 2024).
heart failure (1 paper, 2018). Inability of the heart to pump blood at an adequate rate to meet tissue metabolic requirements. "Dhrs7c has been demonstrated to be downregulated by adrenergic stimulation with both phenylephrine (α-adrenergic) and isoproterenol (β-adrenergic), and in several heart failure models, including biopsies from patients with heart failure." (PMID 30213070, 2018).
cancer (2 papers, 2020 to 2024). A tumor composed of atypical neoplastic, often pleomorphic cells that invade other tissues. "A summary of the models used for building a classifier capable of discriminating between cancer and normal samples based on the expression of seven features: ESM1, DHRS7C, OTOP3, AADACL2, LPHN3, GABRD, and LPAR1." (PMID 39484215, 2024). "A feature space of just seven biomarkers, namely ESM1, DHRS7C, OTOP3, AADACL2, LPHN3, GABRD, and LPAR1, was sufficient to optimize a RandomForest model that achieved > 98% balanced accuracy (and performant recall) of cancer vs. normal on external validation." (PMID 39484215, 2024).
tumor (2 papers, 2024 to 2025). "Knockout of these genes, except for DHRS7C, which was shown to promote tumor colony growth." (PMID 39605490, 2024).
DHRS7C also shares sentences with these, for which no sentence is quoted: pulmonary hypertension (1 paper).